MUC1 (mucin 1, cell surface associated)
Diseases named in the same sentence as MUC1 in open-access papers (continued):
Sharing a sentence is not in itself a finding about the gene and the disease.
tumor (continued). "In conclusion, at least three fully human anti-MUC1 antibodies that were identified through prophylactic vaccination can facilitate ADCC, ADCR, ADCP, and ADCT on tumor targets." (PMID 39449327, 2024). "The results of cell co‐culture and spatial transcriptome assays confirmed that MUC1 and FGF7 mediated the communication between tumour cells and CAFs to a certain degree." (PMID 38778448, 2024). "CAR‐T cells with mucin‐1 (MUC1) and prostate stem cell antigen (PSCA) cannot eliminate tumor cells but the combined therapy showed a better anti‐tumor effect than single CAR‐T cell therapy." (PMID 38456710, 2024). "Cancer antigen (CA15-3), part of the mucin-1 (MUC-1) glycoprotein family, is overexpressed in cancers and is recognized as a useful tumor marker due to its altered glycosylation." (PMID 39742378, 2024). "MUC1 and PSCA CAR-T cells have been found to show independent and synergistic anti-tumour effects in a patient-derived xenograft model of NSCLC." (PMID 38475858, 2024). "Key markers for alveolar dysfunction include Krebs von den Lungen-6 (KL-6), mucins (MUC-1, MUC-4, MUC-5, MUC-16), tumor markers (CA 15-3, CA 125, CA 19-9), surfactant proteins (Sp-A, Sp-D), and club cell secretory protein (CC16)." (PMID 39682582, 2024). "Remarkably, the tumor size decreased significantly to 12 mm, a 65.7% reduction, after combined therapy with eight doses of WT1/MUC1-DC and erlotinib for 237 days." (PMID 38336778, 2024). "We focused on the functions of MUC1 and FGF7 in cell communication since they showed a remarkably high expression in tumour cells and CAFs, respectively." (PMID 38778448, 2024). "The anti-Tn-MUC1 CAR T cells exhibited target-specific cytotoxicity and effective tumor growth inhibition." (PMID 38611013, 2024). "The overexpression of mucin proteins, such as MUC1, MUC2, and MUC5AC in MCA tumors that form a mucous layer protects tumour cells against immunotherapy." (PMID 38778448, 2024). "Here, we constructed a novel DNA vaccine (XCL1-MS) that expresses XCL1, MUC1 and survivin fusion antigens to target cDC1, aiming to induce a robust CD8+T cell response to inhibit tumor development." (PMID 38339158, 2024). "Extensive research has established MUC1 and MUC16 as key players in cancer development, with expression patterns significantly influencing tumor progression and serving as vital prognostic markers." (PMID 38361923, 2024). "Combination therapy with mucin 1 (MUC1)-targeted CAR-T cells resulted in compounded effect, substantially reducing tumor size more than monotherapy." (PMID 39759220, 2024). "Tumor markers CA 15-3, CA 27.29, and MCA are antigens and have unique tandem repeats containing highly immunodominant epitopes in the structure of the MUC1 molecule." (PMID 39456554, 2024). "By visualizing the expression of MUC1 and ELF3 genes in their spatial locations in the EC, we found that these two genes were mainly enriched in the tumor region." (PMID 38517922, 2024). "Anti-tumor activity at low effector to target (E:T) ratios was compared in co-cultures with MDA-MB-468 cells and BxPC3 pancreatic tumor cells (also MUC1+ ErbB+), which respectively are sensitive and moderately resistant to CAR T cell killing." (PMID 38745414, 2024). "The bacterium downregulates MUC1 and CXCL17 expression, which contributes to the reversal of the immunosuppressive tumor microenvironment (TME), leading to OSCC growth inhibition." (PMID 37666495, 2024). "A larger collection of normal samples and tumor samples with paired tumor-adjacent tissues need to be examined to better elucidate the potential toxicity of targeting EGFR and MUC1." (PMID 39664199, 2024). "In detail, the OC tumor tissue and PSO showed MSLN expression on some cells, as well as positive expression of MUC1 and CD276." (PMID 38162496, 2023). "Immunohistochemical results of the perihilar tumor showed MUC1 (2 +), MUC2 (-) and MUC5AC (3 +), and the BilIN lesions exhibited MUC1 (-)." (PMID 37721561, 2023).
tumor (continued). "At the plasma membrane in unpolarized epithelia during tumor progression, EGFR forms a complex with MUC1." (PMID 37720348, 2023). "Using 10 human tumor cell lines exposed to 153Sm-EDTMP, at least two of the five surface molecules (Fas, CEA, MUC-1, MHC class I, and ICAM-1) on each cell line were upregulated." (PMID 36632233, 2023). "All tumor cells showed high expression in signature genes of pancreatic epithelial lesion, like KRT19, MUC1, EPCAM and CEACAM6." (PMID 37007745, 2023). "The DNA aptamers, for example, attach to internalized tumor markers such as CD33, CEA, MUC1, and Tn antigens and are introduced into cancer cells via these surface gateways." (PMID 37149607, 2023). "To date, various specific tumor markers, including HER2, PSA, EGFR (epidermal growth factor receptor), EpCAM, and MUC1 (mucin-1) have been used to isolate CTCs; among these, EpCAM has been extensively used." (PMID 37759483, 2023). "In addition, along with well-established clinico-pathological factors (positive nodal status and large tumor diameter), the lack of CXCL13 expression and the expression of MUC1 in the tumor bed were identified as risk factors that are strongly associated with worse RFS and OS, respectively." (PMID 36765559, 2023). "Among them, PSMA, EpCAM (epithelial cellular adhesion molecule), and MUC1 (mucin-1) are three representative targets for aptamer selection using the purified-protein-based SELEX, and for tumor-targeted delivery of aptamer-functionalized nanoparticles." (PMID 37544972, 2023). "A glycoform of serum mucin 1 (MUC1), detected by a combination of monoclonal antibody (mAb) DF3 and mAb 115D8, has long been clinically used as CA15-3 to estimate the tumor burden of breast cancer." (PMID 37002293, 2023). "A group of scientists performed analyses of CK7, CK20, MUC1, and CDX2 in tumour tissues of patients." (PMID 37504367, 2023). "The interactions of EGFR with MUC1 and SNX1 have both been targeted and shown efficacy in animal mouse tumor models." (PMID 37720348, 2023). "Several clinical trials are also currently underway to evaluate the anti-tumor efficacy of CAR T-cells producing antibodies against CTLA-4 and PD-1 in MUC1+, EGFR+, and mesothelin+ solid tumors (NCT03179007, NCT03182816, and NCT03182803)." (PMID 37020537, 2023). "MUC1 regulates tumor cell proliferation, epithelial-mesenchymal transition (EMT), and epigenetics, a vital tumor regulator." (PMID 37664708, 2023). "The addition of MUC1-targeted CAR T cells also showed a synergistic effect, with the overall tumor mass significantly less than in those treated with either MUC1- or PSCA-directed CAR T cells individually." (PMID 37998743, 2023). "As expected, our confocal microscopic data showed that MUC1-CT and p-JAK1 are co-localised in the cytoplasm of tumour cells, predominately close to the nucleus." (PMID 36810913, 2023). "A recent study showed the overexpression of MUC1, MUC19, MUC4, MUC5AC, and MUC5B in the mucinous metaplasia of tissues isolated from Pten conditional knockout mice and human PCa tumor tissues." (PMID 36980526, 2023). "Three TAA (WT-1, MUC-1 and CA125) were found highly expressed by neoplastic EOC cells, suggesting a potential role for TAAs in inducing an anti-tumor response in EOC." (PMID 37868997, 2023). "MUC1 is upregulated in EOC tissues compared with adjacent tissues and positively correlated with tumor staging." (PMID 37664708, 2023). "Entinostat altered the tumor-related antigens, including PSA, brachyury, CEA and MUC1, and elevated the expression of several proteins that governed tumor immune recognition and antigen processing." (PMID 36969235, 2023). "HIPEC treatment restored the tumor suppression activity of the network comprising miR-145-5p and its target genes MYC, EGFR, MUC1, and OCT4." (PMID 37598177, 2023).
tumor (continued). "223Ra significantly enhanced T cell-mediated lysis of each tumor type (MDA-MB-231, ZR75-1, LNCaP, PC3, H1703, and H441 cells) by CD8+ CTLs specific for MUC-1, brachyury, and CEA tumor antigens." (PMID 36632233, 2023). "UQTs did not express such high levels of those genes but did express certain tumor cell markers such as AGR2, mucin 1 (MUC1), and SERPINB126." (PMID 37771785, 2023). "A high concentration of lymphocytes and dendritic cells, as well as genetic TME markers such as MUC-1 and CXCL13 in the residual tumor, are valuable prognostic factors of survival and relapse in TNBC patients." (PMID 36765559, 2023). "Several known stem markers, including the EPCAM, MUC1 and CD44 signatures, promote transformation and tumour progression." (PMID 36661191, 2023). "The serum tumour marker, CA19-9 and the mesothelial cancer tumour marker, sialylated HEG1, are well-known examples for glycan alteration of MUC1 accompanied by malignant transformation." (PMID 37031283, 2023). "Another antigen expressed on NSCLC tumors is the mucin 1 (MUC-1) glycoprotein, which stimulates tumor cell proliferation pathologically via its cell surface receptor interaction." (PMID 36810079, 2023). "In this study, we constructed a novel T cell-engaging BsAb targeting MUC1 and the CD3 antigen, which can bind T cells and tumor cells simultaneously and redirect T cells to kill tumor cells." (PMID 37489369, 2023). "The delivery of ectopic miR-145-5p through the development of miRNA-145-based magnetic nanoparticle formulation downregulated oncogenic targets such as MUC1, OCT4, and EGFR, thereby efficiently inhibiting tumor growth and metastases in mice." (PMID 37598177, 2023). "Although ErbB and MUC1 provide promising targets for HNSCC and OSCC, the major challenge posed by the immunosuppressive TME in these tumours limits CAR-T cell persistence and efficacy." (PMID 39935547, 2023). "Detection of abnormal increases in MUC1 in the blood can offer new opportunities for CRC early diagnosis, tumor staging, and clinical treatment." (PMID 36839042, 2023). "They identified the CAR (chimeric antigen receptor) target antigen mucin 1 (MUC1) in organoids as well as the corresponding original tumor and produced CAR-T cells against MUC1, which showed significant cytotoxic effects in the organoids." (PMID 37047203, 2023). "The MUC1 aptamer-Dendrimer-epirubicin conjugate and AS1411 aptamer-Dendrimer-epirubicin showed 1802mm3 and 850mm3 of tumor volume after 16 days of treatment." (PMID 37149607, 2023). "We performed IHC staining that showed the tumor cells in mass (I) diffusely and strongly expressed GATA3, MUC1, EMA, E-cadherin, 34bE12, Ksp-cadherin, CK7, and PAX-8, while CD117, CAIX, CK20, RCC, and TFE3 were negative." (PMID 37924117, 2023). "Overall, mRNA expression of MUC1, MUC5AC, and MUC6 was significantly higher in the paired adjacent non-tumor tissues compared to the tumor and FD tissues." (PMID 37085819, 2023). "In contrast to previous studies that injected MUC1-expressing tumor cells to induce cancer, here, we optimized the azoxymethane-dextran sulfate sodium (AOM-DSS) model in MUC1.Tg mice to induce colorectal carcinogenesis." (PMID 36980805, 2023). "In this study, we screened 19 genes associated with ferroptosis, of which 10 FerDEGs such as TLR4, KRAS and HSF1 were highly expressed and 9 FerDEGs such as MUC1, PROM2 and MT1G were lowly expressed in tumour tissue." (PMID 36936437, 2023). "The findings illustrated that the levels of MUC1 and MUC5B mRNA expression changed considerably across various tumour stages (P < 0.05)." (PMID 36059804, 2022). "Tumor cells overexpress MUC1 and MUC4 on the surface, both of which exhibit altered glycosylation, potentially representing tumor-specific targets." (PMID 36291752, 2022).
tumor (continued). "Previous studies and trials have demonstrated that tumor antigens, Her-2, CEA, and MUC-1, are safe and can induce immune system responses." (PMID 35090304, 2022). "As mentioned in previous studies, MUC1 is a glycoprotein highly expressed on the surface of many tumor cells, and it is a TAA with great potential for tumor-targeted therapy development." (PMID 35891256, 2022). "Next, we further tested the inhibitory effect of this novel MUC1-Vax vaccine on MUC1+ and PDL1+ tumor growth in mice." (PMID 35891256, 2022). "In this study, we construct a novel tumor vaccine (SZU251 + MUC1 + Al) with three components: a small-molecule TLR7 agonist synthesized for the first time (SZU251), an MUC1-related peptide (MUC1), and an aluminum adjuvant (Al)." (PMID 36499455, 2022). "Conversely, in low MUC1 expressing PDA cells, TGF-β preserves its tumor-suppressive function and inhibits phosphorylation of JNK and stabilization of c-Myc." (PMID 35237602, 2022). "Using in vivo PDX subcutaneous mouse models and in vitro models, the combination of CAR-T cells targeting MUC-1 and PSCA substantially inhibited tumor growth and PSCA- and MUC-1–expressing NSCLC cell proliferation." (PMID 35720364, 2022). "Both CAR MUC1 T cells significantly upregulated TIM3 and LAG3 expression after coculture with tumor cells." (PMID 36457849, 2022). "MUC1 mRNA nanovaccine and anti-CTLA-4 mAb resulted in a significantly greater level of apoptosis in tumor cells when compared with PBS control group." (PMID 34875483, 2022). "Ex vivo targeting of MR-bearing macrophages with oxi-mannan-MUC1 followed by adoptive transfer, which is efficient in presenting MUC1 to T cells, results in high-frequency CTL generation and protection against a tumor challenge." (PMID 36560459, 2022). "However, testing of postoperative levels and additional assessment after chemotherapy might be more informative for analyzing the usefulness of MUC1 in relation to the efficacy of chemotherapy and other biological effects, such as its role in early systemic tumor spread." (PMID 35406491, 2022). "If indeed TGF-β signaling is critical for the aggressive growth of high-MUC1 PDA tumors, then neutralizing TGF-β with an antibody in vivo would dampen tumor growth." (PMID 35237602, 2022). "Some targetable antigens are mucin-1 (MUC1), mesothelin (MSLN), and CEA, while CART cells against the tumor-specific antigen (TSA) are currently under study." (PMID 35743107, 2022). "Common epithelial and tumor markers were expressed to a variable extent: CD326 (EpCAM) (98.6% ± 1.7, MFI: 40.6 ± 3.1), CD227 (MUC-1) (58.4% ± 2.8, MFI: 7.8 ± 0.1), and CD66adecb (CEA) (38.2% ± 0.2, MFI: 5.0 ± 0.2)." (PMID 36761421, 2022). "It represented a stronger prediction factor than tumor grade, stage or classical PDAC markers such as CEA, MUC16, MUC1, CA199, KRT19 and NSE, and also performed better than any m5C-score gene taken individually." (PMID 36060802, 2022). "These aberrantly expressed glycoproteins, including MUC1, MUC4, and MUC13 play important roles in tumor progression and treatment and are commonly referred to as tumor-related glycoproteins." (PMID 36118865, 2022). "MUC1-specific CAR with the signalling domain CD28–CD137 and a truncated PD-1 peptide on the NK92 cell were able to lyse MUC1-positive tumour cells in vitro and in vivo." (PMID 35453554, 2022). "Following confirmation of anti‐MUC1 nanobody’s cross‐reactivity with mouse MUC1, administration of this nanobody in SMMT demonstrated a significant tumor growth suppressive effect." (PMID 34694686, 2022). "Other MUC1 and CEA vaccines have been tested in metastatic cancer patients, showing them to be safe and induce anti-tumor immunity." (PMID 35248049, 2022). "TAAs are expressed at high levels in proliferating tumour cells; for example, tumour cells express HER2, MUC1 and MAGE." (PMID 36016159, 2022). "GALNT3 can glycosylate MUC1, which further activates the PI3K/Akt pathway and promotes tumour proliferation and invasion." (PMID 35610231, 2022).
tumor (continued). "GO203 inhibits MUC1 function by blocking the MUC1-CQC motif, which has been reported to effectively hinder cell proliferation and xenograft tumor growth." (PMID 36289190, 2022). "CA15-3 is carbohydrate-containing protein antigen of the transmembrane glycoprotein MUC-1, which appears to inhibit tumor cell lysis and reduce cell-cell interactions." (PMID 35634442, 2022). "The expression of MUC1 in Capan-2 and CFPAC-1 tumor tissue was examined by immunostaining with the anti-MUC1-CT antibody." (PMID 36572921, 2022). "For example, the miR-125 as a tumor suppressor reduces the antiapoptotic effect of the MUC1 and Bcl-2 genes and suppresses vascular endothelial growth factor (VEGF) expression, thereby inhibiting tumor proliferation and metastasis formation." (PMID 35326471, 2022). "After exposure to β− particle emission using Sm-153, a bone-seeking radionuclide used to palliate metastatic bone pain, different human tumor cell lines demonstrated upregulation of at least two of the following markers: Fas, MHC-1, ICAM-1, CEA, and MUC-1." (PMID 36497086, 2022). "MUC1 is a TAA with great potential, and the immune checkpoint PD-L1 also has great potential for tumor treatment." (PMID 35891256, 2022). "On the other hand, in low-MUC1 cells (MiaPaca2), TGF-β serves as a tumor suppressor and therefore when the tumor suppressing effect of TGF-β was neutralized, tumor growth was increased, albeit not significantly." (PMID 35237602, 2022). "Therefore, tandem repeats of MUC1 protein backbone are more easily and abundantly accessible for the development of new protein–protein interactions, which can result in activation of several signaling pathways, further accelerating tumor growth, angiogenesis, invasion, and metastasis." (PMID 34694686, 2022). "This confirmed that the anti‐MUC1 nanobody of present study is also capable of binding with mouse MUC1 antigen, and thus, SMMT model can be used for evaluating nanobody’s tumor suppressing effects in vivo." (PMID 34694686, 2022). "In an analysis of a tumor cell/immune cell mixture, a clean separation between tumor (HER2+/EpCAM+/MUC1+/EGFR+) and immune cells (CD45+) was observed." (PMID 35508767, 2022). "MUC1 is involved in the vital process of HIF-1α regulating tumor glucose metabolism, leading to increased dependence of tumor cells on glucose and the increase of corresponding pyrimidines, thereby improving the intrinsic level of dCTP." (PMID 35709153, 2022). "Gatipotuzumab is another mAb used in phase I/II clinical trials for solid tumors (NCT03360734, NCT01222624) that binds to STn-bearing MUC1 and prevents its interactions with siglec-9, to instigate ADCC against the tumor cells." (PMID 36686742, 2022). "Risk factors with a p value less than 0.1, i.e., tumour grade, tumour stage, CA19-9 level, adjuvant chemotherapy, adjuvant radiotherapy, MUC1 expression, and MUC2 expression, were integrated to make multivariate analysis." (PMID 35910854, 2022). "Previous publications have reported contradicting results—both upregulation and/or downregulation of MUC1, CD44, and HA have been connected to tumor progression." (PMID 36359337, 2022). "Consistently, YBX1, MUC1 and MUC13 were upregulated in tumour tissues of patients compared to the paracancerous tissues." (PMID 35292781, 2022). "In in vitro breast cancer, the proliferation and anti-tumor efficacy of biCAR-T cells depend on combinational targeting of HER2 and MUC1 simultaneously with CD3z and other co-costimulatory molecules in one T cell." (PMID 35326556, 2022). "The MUC1 protein is related to the interactions between cells or between cells and the extracellular matrix (ECM), which, thus, possibly promotes tumor cell metastasis at the primary site." (PMID 35883508, 2022).